C11orf65 (chromosome 11 open reading frame 65)
Description:
Acts as an inhibitor of mitochondrial fission. Interacts with MFF and prevents DNM1L recruitment to mitochondria, promoting a more fused mitochondrial network.
Synonyms: MFI; MGC33948
Tractability: No criterion of Open Targets' tractability assessment is met for any kind of drug.
Gene: Protein-coding gene on chromosome 11 (108,308,519 to 108,467,531, reverse strand). Ensembl gene ENSG00000166323.
Subcellular location: Cytoplasm, cytosol; Mitochondrion outer membrane
Gene Ontology:
Molecular function: protein binding
Biological process: negative regulation of establishment of protein localization to mitochondrion; negative regulation of mitochondrial fission
Cellular component: cytosol; mitochondrial outer membrane
Genetic constraint (gnomAD): Loss-of-function variants: 24 observed, 20.08 expected, observed/expected ratio (o/e) 1.2, 90% interval 0.86 to 1.67. The upper end of that interval is the gene's LOEUF score, 1.67, which puts it in group 6 of 6, group 1 being the genes least tolerant of losing a copy. Missense variants: 280 observed, 290.83 expected, observed/expected ratio (o/e) 0.96, 90% interval 0.87 to 1.06. Synonymous variants: 80 observed, 93.07 expected, observed/expected ratio (o/e) 0.86, 90% interval 0.72 to 1.03.
Homologues: Orthologues: chimpanzee C11H11orf65 (100% identical), rabbit C11orf65 (78% identical), dog C11orf65 (77% identical), mouse 4930550C14Rik (70% identical), rat C8h11orf65 (68% identical), pig C11orf65 (67% identical), guinea pig C11orf65 (62% identical).
Diseases named in the same sentence as C11orf65 in open-access papers:
C11orf65 is named in the same sentence as 3 diseases in open-access papers, as found by Europe PMC text mining. Sharing a sentence is not in itself a finding about the gene and the disease.
C11orf65 shares sentences with these, for which no sentence is quoted: cancer (2 papers); biliary tract cancer (1); neurodegenerative disease (1).